SIRT6 (sirtuin 6)
Diseases named in the same sentence as SIRT6 in open-access papers (continued):
Sharing a sentence is not in itself a finding about the gene and the disease.
tumor (continued). "We thus hypothesized that the tumor suppressing function of SIRT6 could be through regulating R-Ras2." (PMID 28406396, 2017). "Knowing that SIRT6 downregulation promotes muscle atrophy, we next tested whether restoring SIRT6 expression can overcome the inhibitory effect of tumor-derived cytokines on muscle cell growth." (PMID 28928419, 2017). "Utilizing this mutant, we first investigated whether the defatty-acylase activity of SIRT6 contributes to tumor suppression and aimed to identify the defatty-acylation substrate protein that is important for this function." (PMID 28406396, 2017). "Thus, the defatty-acylation and suppression of R-Ras2 is a major contributor to the tumor suppressor role of SIRT6." (PMID 28406396, 2017). "Interestingly, investigations into the exact role of SIRT6 in cancer appears to result in mixed answers, with available evidence for both tumor promoter as well as tumor suppressor roles of this sirtuin." (PMID 29234488, 2017). "However, sirtuin-6 (SIRT6) is highly expressed in ECs, fibroblasts, embryonic stem cells and tumor cell lines, where it protects DNA repair and telomere maintenance." (PMID 29267201, 2017). "Our study establishes lysine fatty acylation as a previously unknown mechanism that regulates the Ras family of GTPases and provides an important mechanism by which SIRT6 functions as a tumor suppressor." (PMID 28406396, 2017). "In human HCC, SIRT6 may act as a tumor suppressor, given that ectopic SIRT6 overexpression inhibits HCC cell growth." (PMID 27777384, 2016). "Therefore, the role of SIRT6 in cancer is complex, with some studies supporting a tumor-suppressive role, and others a cancer-promoting role." (PMID 27777384, 2016). "As with SIRT1, SIRT6 plays both tumor suppressing and promoting roles." (PMID 27916001, 2016). "SIRT6 is regarded as a tumor suppressor partly due to its pivotal role in cancer metabolism." (PMID 27916001, 2016). "Contradictory findings as to whether SIRT6 is a tumor repressor or tumor promoter have been reported, even in the same tissue, such as the pancreas or breast." (PMID 27824900, 2016). "Nevertheless, the finding that overexpression of SIRT6 triggers heightened apoptotic response specifically in cancerous cells but not in normal cells, further reinstates the role of this sirtuin as a potent tumor suppressor." (PMID 25907989, 2015). "Our finding on the repression of SIRT6 transcription by E2F1 will broaden the therapeutic opportunities to enhance SIRT6 tumor suppressor activities with compounds like CDK4/6 inhibitor, which retains E2F1 in the RB-E2F1 complex by diminishing the phosphorylation of RB by CDK4/6." (PMID 25816777, 2015). "In addition to these members of the ARTD family, recent studies revealed that SIRT4 possesses tumor suppressor function, whereas SIRT6 has been reported to have both tumor suppressive and promoting functions." (PMID 26426055, 2015). "SIRT6 has been reported to have tumor suppressive functions." (PMID 26426055, 2015). "Whereas the preponderance of the evidence suggests that SIRT1 in many contexts promotes cancer metabolism by working in conjunction with HIF and MYC family proteins, SIRT3, SIRT4 and SIRT6 all inhibit distinct aspects of the metabolic alterations observed in tumor cells." (PMID 25085992, 2014). "In addition, another up-regulated miRNA, the miR-296 was predicted to regulate the tumor suppressor Sirt6." (PMID 23593434, 2013). "Sirt6 may promote tumor growth and is a potential target for tumor therapy." (PMID 41530841, 2026). "However, few studies have investigated whether—and how—SIRT6 influences mitochondrial function in tumor systems." (PMID 41362737, 2026). "Furthermore, our research reveals that SIRT6 exerts a dual function in determining the "survival or death" fate of cardiomyocytes and tumor cells by inducing metabolic reprogramming, characterized by enhanced mitochondrial respiration and suppressed glycolysis." (PMID 40093797, 2025).
tumor (continued). "Paradoxically, SIRT6 may also act as a tumor suppressor under specific conditions." (PMID 41463311, 2025). "Although still at the preclinical stage, several targets for the treatment of HCC, such as CBP (CREB binding protein) and SIRT6 (Sirtuin 6), which are involved in oncogenic gene regulation, have been successfully degraded in vitro or in vivo in mouse models, resulting in reduced tumor progression." (PMID 41445747, 2025). "Specifically, SIRT1, SIRT2, SIRT6, and SIRT7 are implicated in promoting PCa progression, while SIRT5 displays a paradoxical role, simultaneously aiding DNA repair and inhibiting apoptosis, yet fostering tumor growth through androgen receptor (AR) interactions." (PMID 39796040, 2024). "Given the significant deletions observed on chromosome 15 in various cancers, including PCa, further investigation into these interactions could unveil novel therapeutic strategies aimed at reinstating SIRT6 function and exploiting its regulatory capabilities to combat tumor growth and metastasis." (PMID 39796040, 2024). "Thus, the bioinformatic analysis suggested that SIRT6 may be a tumor suppressor in BLCA, and low levels of SIRT6 predict poor prognosis." (PMID 39709438, 2024). "Besides, it is still unknown whether SIRT6 is aberrantly expressed in BLCA that influences tumor progression." (PMID 39709438, 2024). "Taken together, it was discovered that SIRT6 may act as a tumor suppressor by regulating the expression of several genes involved in DNA repair, cell cycle progression, and apoptosis, all of which are essential for preserving genomic integrity and preventing the growth of cancer." (PMID 38203666, 2023). "Also, SIRT6 over-expression is maintained in Delta16HER2/SIRT6-OE primary tumor cell cultures." (PMID 38081972, 2023). "However, at later stages, enhanced SIRT6 activity may protect cancer cells against further mutagenesis and oxidative stress which could negatively impact tumor growth." (PMID 38081972, 2023). "Additionally, the TCGA dataset was used to assess SIRT6's prognostic value in various tumour types." (PMID 35172823, 2022). "Previous studies have proven that SIRT6, as a key chromatin regulator, remodels chromatin by promoting chromatin relaxation, although it has diverse biological functions, such as genome stability, glucose metabolism, and tumor suppression, through multiple pathways." (PMID 35668088, 2022). "In short, similar to SIRT4 and SIRT5, SIRT6 might have a tumor suppressor function in GC." (PMID 36358890, 2022). "However, in other cancers, SIRT6 exhibits tumor suppressor activity." (PMID 35463332, 2022). "Therefore, a hypothesis that SIRT6 may regulate tumor proliferation by histone lactylation in TPCs warrants additional research." (PMID 35224683, 2022). "Interestingly, SIRT6 functions as both a tumor suppressor and an oncogenic protein." (PMID 35890276, 2022). "Both of SIRT6's functions in the same tumour type may be related to autophagy." (PMID 35172823, 2022). "Furthermore, USP10 could deubiquitinate sirtuin 6 (SIRT6) to antagonize transcriptional activation of c-Myc oncogenes to inhibit tumor formation." (PMID 35433424, 2022). "Indeed, whilst showing a tumor-suppressor role in this type of cancer, the authors suggest that SIRT6 inhibition may enhance sensitivity to chemotherapeutics consequently improving patient prognosis." (PMID 33800266, 2021). "Their findings also support our results, wherein we observed that in the tumour setting, SIRT6 over‐expression inhibited WNT4 expression in the skeletal muscle and downregulated circulating levels of WNT4, which might have contributed to maintain plasma insulin levels in Tu‐Sk.T6Tg mice." (PMID 34212132, 2021). "Therefore, SIRT6 plays an important role in tumor progression." (PMID 34225779, 2021). "Moreover, several studies have revealed that Sirt6 is involved in tumor suppression." (PMID 33727672, 2021).
tumor (continued). "We found that in vivo moderate over‐expression of SIRT6 in skeletal muscle not only inhibited myostatin expression in autocrine manner but also normalized insulin levels and downregulated secretion of non‐esterified free‐fatty acid in the plasma via paracrine signalling in tumour‐bearing mice." (PMID 34212132, 2021). "In the case of SIRT6, the two-pronged regulation of both histone deacetylation and ACLY-dependent histone acetylation may help maintain the stability of tumor suppressive gene expression programs and protect against potential effects of metabolic fluctuations on SIRT6 or ACLY activity." (PMID 34573442, 2021). "Importantly, SIRT6 plays a tumor suppressor role in the maintenance of cancer." (PMID 31842909, 2019). "This review focuses on one the mammalian sirtuins, SIRT6, which has emerged as an important regulator of longevity and appears to have multiple biochemical functions that interfere with tumor development and may be useful in cancer prevention and for site-specific treatment." (PMID 31591350, 2019). "Therefore, depending on its biological mechanisms of action in each tumor, the inhibition or activation of SIRT6 might have therapeutic value." (PMID 31591350, 2019). "This duality relates to SIRT6, and may result from tissue and tumor type-specific function." (PMID 31591350, 2019). "Accordingly, SIRT6 deletion, observed in different tumours, like colon, pancreatic and hepatocellular carcinomas, leads to increased H3K9ac levels resulting in glycolytic gene expression upregulation promoting cellular transformation and, consequently tumour growth and progression." (PMID 30356832, 2018). "Considering the wide range of processes that SIRT6 seems to be potentially involved in, it comes as no surprise that it may also be linked to cancer progression and tumor growth." (PMID 29966233, 2018). "However, it was unclear whether and how this activity of SIRT6 contributes to its role as a tumor suppressor." (PMID 28406396, 2017). "In addition, SIRT6 is identified as a tumor suppressor that regulates cancer metabolism." (PMID 27659520, 2017). "Studies show SIRT6 represses aerobic glycolysis in cancer cells and SIRT6 deficiency contributes to tumor formation even without any oncogene activation, indicating the glucose metabolic reprogramming is not a mere consequence of tumorigenesis but also one of its main drivers." (PMID 27916001, 2016). "However, other data point to a Janus-faced role of SIRT6 in neoplasia." (PMID 25085992, 2014). "Thus, some sirtuins, such as SirT2 and SirT6, seem to work as tumor suppressors." (PMID 25397683, 2014). "However, it is currently unknown whether elevated SIRT6 activity confers increased tumor suppression capacity." (PMID 25085992, 2014). "However, in some tumor types, SIRT6 function might be recruited to promote stress resistance, i.e. against genomic insult or other forms of cellular injury." (PMID 25085992, 2014). "Because different tumor cell types show different sensitivities to UBCS039 treatment and the subsequent deacetylation activity of Sirt6, these tumor cell lines show different tumor growth levels after injection into mouse models." (PMID 41530841, 2026). "Both the SIRT6 overexpression group and the TFAM knockdown group showed significantly smaller tumor volumes compared to the control group." (PMID 41362737, 2026). "In the tumor cells that were given UBS039, the PD-L1 and Sirt6 expression levels were also elevated, as was PD-1 expression in cocultured CD4 + T cells." (PMID 41530841, 2026). "Pharmacological inhibition of SIRT6 via OSS-128167 significantly attenuated LPE18:1-driven lipid accumulation and tumor cell growth." (PMID 41354870, 2025). "Genetic or pharmacological inhibition of the CAPZA1/SIRT6 axis can reverse LPE18:1-induced lipid deposition and tumor progression in xenograft models." (PMID 41354870, 2025).
tumor (continued). "In contrast, in triple-negative breast cancer, upregulation of SIRT6 by icariin suppresses NF-κB/EMT signaling, induces redox-mediated apoptosis, and enhances anti-tumor immunity, which underscores its tumor-suppressive potential." (PMID 41463311, 2025). "Collectively, these findings underscore the dual nature of SIRT6 in CRC—acting as a metabolic and epigenetic regulator that can either suppress or facilitate tumor progression." (PMID 41463311, 2025). "SIRT6 upregulated by USP10 stabilizes GPX4, thereby attenuating erastin-induced ferroptosis and enhancing tumor growth, migration, and invasion." (PMID 41463311, 2025). "Collectively, these findings highlight SIRT6 as a double-edged regulator in NSCLC, functioning as either an oncogene or tumor suppressor depending on the cellular context, and underscore its potential as both a prognostic biomarker and a therapeutic target." (PMID 41463311, 2025). "SIRT6 can regulate gene expression of DNA stability and immunity, while SIRT7 promotes tumor metastasis through upregulation of E-cadherin expression." (PMID 41011152, 2025). "Although SIRT6 can be involved in deacetylation, mono-ADP-ribosylation, and defatty-acylation, its tumor suppressor functions primarily depend on its deacetylation activity on histone acetylation." (PMID 38954215, 2025). "The intricate role of SIRT6 in CRC echoes the pleiotropic nature of TGF-β, which acts as a tumor suppressor in early-stage tumors but an oncogene in advanced cancer." (PMID 38891773, 2024). "Among the sirtuins, SIRT1, SIRT3, SIRT4, and SIRT6 have been identified as significant targets for anti-tumor treatments; SIRT4 has been proposed as a tumor-suppressor protein, reducing glutamine entry into mitochondria in response to DNA damage." (PMID 39195514, 2024). "With the exception of HDAC1, SIRT6, and SIRT7, most HDAC genes were down-regulated in various tumor types." (PMID 39512688, 2024). "Of note, the spleen was enlarged and become calcified in Sirt6-LKO and ob/ob mice (Fig. EV5H), indicating the incapacity of an immune response to kill the tumor cells." (PMID 38332150, 2024). "Of note, the tumor burden was significantly higher in Sirt6-LKO mice, especially in those tumor volumes less than 5 mm (Fig. EV5C)." (PMID 38332150, 2024). "The role of SIRT6 in CRC seems to be multifaceted, as certain studies support its cancer-suppressive function, while others indicate a tumor-promoting effect." (PMID 38891773, 2024). "In KLF10-depleted PDAC models, SIRT6 plays a pivotal role in reversing the malignant phenotypes, including increased EMT and glycolysis, which are characteristic of aggressive tumor progression." (PMID 39682281, 2024). "One significant pathway involves the interaction between SIRT6 and Krüppel-like factor 10 (KLF10), a known tumor suppressor." (PMID 39682281, 2024). "SIRT6, an NAD-dependent histone deacetylase and a recognized tumor suppressor, emerges as a critical regulator of these RUNX2-mediated metabolic changes." (PMID 38203666, 2023). "Studies have shown that the expression of SIRT2, SIRT3, SIRT6, and SIRT7 is increased in tumor-stage 1-4 subgroups, SIRT1 expression is increased in tumor-stage 1, and the expression of SIRT4 is decreased." (PMID 37096064, 2023). "Low SIRT6 expression increases the acetylation of H3K9 and levels of Glut1 and PDK1, enhances glycolysis, and increases the proliferation ability of tumor cells." (PMID 35463332, 2022). "Consistent with the tumor volume data, SIRT6, HIF-1α, HK2 and Ki-67 protein levels were lower in the PC9/ER/shSIRT6 tumor tissue samples than in the PC9/ER/shCtrl tissue samples." (PMID 35915188, 2022). "In terms of KAT5, SIRT4, SIRT6 and SIRT7, these four genes demonstrated higher expression in tumours than in adjacent tissues." (PMID 36308411, 2022). "In cancer, SIRT1 and SIRT6 act as tumor suppressors, whereas SIRT7 is responsible for tumor phenotype maintenance, and its expression is increased in many cancers." (PMID 36012298, 2022).
tumor (continued). "SIRT6 increases extracellular signal-regulated kinase (p-ERK) 1/2 phosphorylation and activates matrix metalloproteinase 9 (MMP9) to facilitate tumor cell migration and invasion." (PMID 35463332, 2022). "Sirtuin 6 (SIRT6) is one of a few downstream genes that are bound by KLF10 and govern cancer metabolism and tumor progression." (PMID 34702956, 2021). "In this study, we have identified a novel function of SIRT6 in controlling nuclear levels of ACLY and ACLY-dependent tumor suppressive gene regulation." (PMID 34573442, 2021). "Specifically, we crossed MMTV-PyMT+/− male mice with Sirt6+/− female animals and compared tumor latency and mouse survival between MMTV-PyMT+/−; Sirt6+/+ and MMTV-PyMT+/−; Sirt6+/− mice." (PMID 33482921, 2021). "Overall, these findings indicate that SIRT6 depletion reduces OXPHOS and energy status in BC cells of a murine and human source and point to a probable mechanism for the reduced tumor growth occurring in response to SIRT6 depletion." (PMID 33482921, 2021). "The tumor promoting capacity of SIRT6 has also been demonstrated in skin SCC, where SIRT6 is upregulated." (PMID 33800266, 2021). "A marked increase in tumor growth and metastasis was detected in PC3M-luc-SIRT6-OE group compared with the control group." (PMID 33995674, 2021). "Since in MMTV-PyMT+/−; Sirt6+/− mice, Sirt6 deletion affects all bodily tissues, the observed delay in tumor development and the corresponding enhancement of mouse survival could in principle reflect non-cell-autonomous anticancer effects (i.e., effects unrelated to Sirt6 deletion in tumor cells)." (PMID 33482921, 2021). "The expression of miR-25, SIRT6, Lin28b, and NRP-1 in tumor tissues was measured by western blot assay and qRT-PCR." (PMID 33510943, 2021). "We then showed that the activation of SIRT6 by MDL-811 suppressed the transcription of CYP24A1, which synergistically enhanced the anti-tumor effect of vitamin D3 (VD3) in CRC." (PMID 32483423, 2020). "It has been found that depletion of Sirtuin 6 (Sirt6) suppressed the number of human nasal epithelial cell cilia, and dramatically induced HMGB1 translocation from nucleus to cytoplasm in an epithelial tumor cell line." (PMID 32629817, 2020). "Finally, SIRT6 could increase the sensitivity to tumor treatment." (PMID 33335996, 2020). "SIRT6 expression was found to be higher in KIRC tissues than in normal tissues and was significantly and positively correlated with tumor stage and histologic grade." (PMID 32158696, 2020). "As shown in our previous study, SIRT6 is upregulated in PTC and promotes tumor invasion and migration by inducing the epithelial-mesenchymal transformation." (PMID 32983963, 2020). "Loss of SIRT6 prompted cells glycolytic path towards lactate production, even under aerobic conditions suggesting that the lack of SIRT6 might provide a growth benefit for tumor cells." (PMID 33255318, 2020). "The expression levels of SIRT1, SIRT3, SIRT5, SIRT6, and SIRT7 were significantly correlated with tumor stage and histological grade." (PMID 32158696, 2020). "MDL-811 treatment led to strong tumor regression in both PDX models, with decreased Ki67 staining and reduced SIRT6-specific histone H3 acetylation marks, consistent with the pharmacological effect of MDL-811 in the CDX model." (PMID 32483423, 2020). "SIRT6 inhibits PCBP2 expression by binding to PCBP2 promoter region and deacetylates H3K9, acting, therefore, as a tumor suppressor." (PMID 31591350, 2019). "MG132 treatment blocked tumor growth inhibition induced by NQO1 knock out, accompanied with increased level of SIRT6 and XIAP." (PMID 31842909, 2019).